IL5 (interleukin 5)
Diseases named in the same sentence as IL5 in open-access papers (continued):
Sharing a sentence is not in itself a finding about the gene and the disease.
allergic rhinitis (71 papers, 2009 to 2026). Inflammation of the nasal mucous membranes caused by an IgE-mediated response to external allergens. "According to the cytokine profile in the preseasonal ASIT regimen, the development of allergic rhinitis was predominantly associated with IL-5 and IL-13 production, and bronchial asthma with IL-4, IL-5, IL-13, and TNF-α, which is consistent with other reports." (PMID 36439113, 2022). "In a mouse model of allergic rhinitis, treatment with geniposide significantly reduced serum levels of IL-4, IL-5, and IL-17." (PMID 41001345, 2025). "In PBMCs from allergic rhinitis patients, 6B12 treatment reduced secretion of IL-5 and IL-13, a key cytokine involved in the pathogenesis of allergic rhinitis." (PMID 40078995, 2025). "In an experimental study in rats with allergic rhinitis, hesperidin significantly reduced the levels of IgE, IL-5, and IL-13 and modulated the oxidative balance." (PMID 41001345, 2025). "After different administrations, CCR3mAb i.p. group had increased trends in Th1 cytokines (IFN-γ and IL-2) compared to allergic rhinitis mice, with statistical significance; and decreased trends in Th2 cytokines (IL-4, IL-5, and IL-13)." (PMID 38212473, 2024). "There is evidence that T cell-mediated Th2 cytokines including IL-4, IL-5, and IL-13 are elevated in patients with allergic rhinitis, and can regulate eosinophil growth and differentiation." (PMID 35831673, 2023). "In an allergic rhinitis mouse model, SHEDs inhibited the Th2 immune response by downregulating IL-4, IL-5, and IL-13 levels in spleen lymphocytes and decreasing the production of serum IgE and IgG1." (PMID 35909660, 2022). "Consuming thyme with an increase in anti-inflammatory cytokine IL-4 and a decrease in IL-5 cytokine control inflammation and improvement in allergic rhinitis symptoms." (PMID 35144653, 2022). "The emerging innovative drugs include mAbs targeting on characteristic pathways of type 2 inflammation, such as those of IgE, the IL-5, and IL-4/IL-13 which are involved in several pathologic condictions including CRSwNP or allergic rhinitis." (PMID 35387050, 2021). "Application of A. cepa on the nasal cavity of BALB/c mice with allergic rhinitis revealed remarkable decreases in IgE and inflammatory cytokines IL-4, IL-5, IL-10, and IL-13." (PMID 34552650, 2021). "Ginsenoside Rd suppressed ovalbumin-induced expression of IgE, IL-4, IL-5, and IL-13 in nasal mucosa and bronchoalveolar lavage fluid and alleviated gut dysbiosis in mice, resulting in the attenuation of allergic rhinitis." (PMID 32326081, 2020). "The serum levels of IL-5 and IL-10 in complication group significantly exceeded those of allergic rhinitis group (P<0.05)." (PMID 30344593, 2018). "The serum levels of IL-5 and IL-10 in the complication group were significantly higher than those of the allergic rhinitis group (P<0.05)." (PMID 30344593, 2018). "This is consistent with our results obtained from a model of allergic rhinitis: the infiltrating eosinophil number and IL-5 mRNA levels in nasal mucosa were significantly decreased in the IL-17A KO-OVA group compared with the WT-OVA group." (PMID 28046055, 2017). "Another study showed that β-glucan administration to subjects with seasonal allergic rhinitis resulted in reduced IL-4 and IL-5 levels." (PMID 27390655, 2016). "A similar boost in circulating IL-5 has been observed in seasonal allergic rhinitis patients 24-hr after nasal allergen challenge." (PMID 23556029, 2013). "On the other hand, these authors observed a significant relation among the increased IL-5 levels, nasal eosinophilic infiltration and the clinical manifestations of allergic rhinitis." (PMID 19488556, 2009). "In a murine model of allergic rhinitis, the IL-5 and IgE levels closely related to the allergic inflammation were significantly reduced after the intranasal administration of an anti-IL-5 ON complexed with chitosan." (PMID 19701125, 2009).
allergic rhinitis (continued). "The authors found that the onset of allergic rhinitis symptoms was delayed in IL-5(-/-) mice." (PMID 40429652, 2025). "Cystatin-SA/SN are cysteine protease inhibitors that enhance eosinophil activation and recruitment through induction of IL-5 and suppress allergic rhinitis symptoms by inhibiting allergenic protease activities and protecting the nasal tight junction barrier in an allergen-specific manner." (PMID 36969262, 2023). "When looking into the literature, a decrease in IL-4, IL-5 and IL-13 after acupuncture could be seen in animal experiments, namely in rats suffering from allergic rhinitis." (PMID 35301577, 2022). "To investigate whether LE_R alleviates allergic reactions in an OVA-induced allergic rhinitis mice model, we used ELISA kits to measure the amounts of the T-helper (Th) type 2 cytokines IL-4 and IL-5 in the serum." (PMID 36142314, 2022). "Additionally, in a double-blinded, randomized, placebo-controlled clinical trial, sulforaphane showed effects in decreasing T2 cytokines such as IL-4, IL-5, and IL-13 in nasal cavity mucus of allergic rhinitis patients." (PMID 34439514, 2021). "Indeed, administration of SP enhances IL-5 mRNA transcription in nasal mucosal tissues of patients with allergic rhinitis." (PMID 23934070, 2013). "IL-5 secretion was especially high in LDHhigh patients, which could be related to the increased eosinophil count in their blood and may explain the higher prevalence of allergic rhinitis within this AD subpopulation." (PMID 40869144, 2025). "However, IL-4, IL-5 and IL-13 levels may be elevated in the nasal secretion of patients with persistent severe allergic rhinitis." (PMID 30846420, 2020). "The aim of this study is to analyze the efficacy of anti-IL5 or anti-ILR5 therapy in patients with severe eosinophilic asthma and persistent allergic or non-allergic rhinitis." (PMID 41598525, 2026). "β-glucan also reduced IL4 and IL5 concentrations and increased IL12 concentrations in individuals with allergic rhinitis." (PMID 38655128, 2024). "This study was conducted on the bank sample before and after the intervention to measure interleukin-4, interleukin-5, and interferon -γ levels with the ELISA test method in a supernatant taken from the PBMC cell culture from 30 allergic rhinitis patients." (PMID 35144653, 2022). "The expression of IL-4, IL-5, and IL-13 mRNA was significantly higher in mice with OVA-induced allergic rhinitis than in the control group; however, they were significantly lower in mice treated additionally with LE_R or CIC." (PMID 36142314, 2022). "It has been reported that an increase in IL-31 levels was detected in patients with allergic rhinitis and IL-31 induced production of IL-4, IL-5 and IL-13 in PBMC and nasal epithelial cells from patients with allergic rhinitis." (PMID 30647024, 2019). "To test this, we intravenously treated LinOVA mice with a mixture of anti-IL-5 antibody and anti-CCL11 antibody and induced allergic rhinitis in the model." (PMID 31766714, 2019). "IL-4, IL-5, IL-8 and IFN-γ cytokines, especially IL-4 and IL-5, mediate and regulate immune and inflammatory reactions in allergic rhinitis." (PMID 19488556, 2009). "At present, no biologics targeting IL-5/IL-5R have been subjected to specific investigation for the treatment of allergic rhinitis." (PMID 40429652, 2025). "Compared to allergic rhinitis mice, CCR3mAb2 and CCR3mAb3 groups had increased trends in Th1 cytokines (IL-2 and IFN-γ), with statistical significance; and decreased trends in Th2 cytokines (IL-4, IL-5, and IL-13)." (PMID 38212473, 2024). "IL-4, IL-5, and IL-13 are produced by TH2 type cells and have cardinal roles in allergic rhinitis." (PMID 31807241, 2019). "In the past, only a limited panel of mainly Th2 mediators–examples being IL-5, IgE, and eosinophils–were taken into account when comparing non-allergic rhinitis patients with allergic rhinitis patients." (PMID 30048449, 2018).
allergic rhinitis (continued). "There was no IL-4 and IL-5 production in the patients, which was expected as both cytokines are typical messengers for type 1 allergic reactions (immediate reaction, e.g. hay fever, allergic rhinitis)." (PMID 35147719, 2023).
Obesity (61 papers, 2011 to 2025). Accumulation of substantial excess body fat. "In general, obesity is associated with elevated levels of cytokines originating from both Th2 and Th1 immune responses, including interleukin (IL)-5, IL-10, IL-12, IL-13, Interferon-gamma (IFN-γ), and tumor necrosis factor alpha (TNF-α)." (PMID 41007770, 2025). "IR can instigate an upsurge of inflammatory cytokines associated with obesity, including IL-1β, IL-2, IL-4, IL-5, IL-6, IL-8, tumor necrosis factor-α, and interferon, which have been robustly linked to the development of PAH." (PMID 38702735, 2024). "Overweight/obesity was also linked to increased plasma levels of IL-5, IL-17A, IL-22, IL-33, TNF-α, and leptin and decreased levels of IL-10." (PMID 39902293, 2024). "The studies report that obesity is associated with significantly elevated levels of Il-5, Il-10, Il-12, Il-13, IFN-γ and TNF-α." (PMID 34444287, 2021). "It has also been reported that γδT cells secreted IL-17A, obesity induced GM-CSF and IL-5, periostin and Elf5 are associated with neutrophils recruitment in the lung." (PMID 33178575, 2020). "Low-grade chronic inflammation associated with obesity has been shown to drive the expansion of CD11b+Gr1+ cells within the lung in an IL-5 and GM-CSF-dependent manner, resulting in an increase in breast cancer pulmonary metastasis." (PMID 31488209, 2019). "Early during infection (i.e., d3 p.i.), obesity was again associated with reduced production of cytokines IL-13, IL-5, IL-12p70, IFNγ, TNFα, IL6, and IL-1β, as well as IL-28b (IFNλ), IL-17, and IL-15." (PMID 26110868, 2015). "Moreover, heightened eosinophil levels in IL-5 overexpressing mice have been linked to resistance against diet-induced obesity, elucidating a potential protective mechanism." (PMID 38235134, 2023). "We aimed to address this gap by determining IL-33 serum level and its downstream type 2 inflammatory cytokines interleukin-5 (IL-5) and interleukin-13 (IL-13) in overweight/obese population, and analyzing the specific associations between IL-33 and obesity metabolic phenotypes." (PMID 33541367, 2021). "Interestingly, BM upregulated specific Th2 cytokines IL-5, IL-10 and IL-13, which have been demonstrated to protect obesity-associated inflammation." (PMID 21639917, 2011). "Therefore, obesity‐induced increases in eosinophil inflammation in the airways of asthmatic mice may be linked to the increased production of IL‐4, IL‐5, and eotaxin." (PMID 37773696, 2023). "The reduced efficacy of mepolizumab (anti‐IL‐5) in severe asthmatics with obesity was reported, and the odds of achieving clinical remission decreased by 59% for those with obesity." (PMID 40329860, 2025). "Th2 cytokines, such as IL-4, IL-5, and IL-13, regulate energy metabolism, insulin resistance, and obesity-related issues." (PMID 41007770, 2025). "This review aims to clarify the role of IL-4, IL-5, and IL-13 in contributing to the immunometabolic changes observed in obesity." (PMID 41007770, 2025). "Preclinical and early clinical research has explored pharmacological strategies to modulate IL-4 and IL-5 in obesity and metabolic dysfunction." (PMID 41007770, 2025). "They observed increased levels of IL-5, IL-13, and CC chemokine receptor type 3 with obesity, the latter involved with eosinophil chemotaxis." (PMID 39427706, 2025). "Together, these studies suggest that IL-5 is a promising yet under-investigated therapeutic target for obesity and metabolic diseases, primarily through approaches that enhance eosinophil activity rather than reduce it." (PMID 41007770, 2025). "In adipose tissue, ILC2s induce the type 2 cytokines IL-5 or IL-13 and increase eosinophils numbers, and M2 macrophages stimulate inflammation, which promotes immunity and metabolic homeostasis and curbs obesity." (PMID 38283340, 2023). "In contrast, IL-5 overexpressing mice show elevated eosinophil levels and resistance to diet-induced obesity." (PMID 38235134, 2023).
Obesity (continued). "As will be discussed in the next section, IL‐5 participates in the event of cytokine storm, is often increased in obesity, and skews the polarization to a Th17 profile and away from the Treg profile." (PMID 35837843, 2022). "Nonetheless, obesity‐related dose of leptin elevated not only the release of IL‐6 and IL‐17, but also IL‐5 and IL‐13 by CD4+ T cells in lean‐derived cell cultures from patients." (PMID 35734271, 2022). "The decrease in the concentration of Th2 cells observed in obesity results in a decrease in the concentration of anti-inflammatory cytokines, such as interleukin 4 (IL-4), interleukin 5 (IL-5), interleukin 10 (IL-10) and interleukin 13 (IL-13)." (PMID 34564433, 2021). "Granulocyte-macrophage colony-stimulating factor (GM-CSF) and interleukin 5 (IL5) were responsible for pro-metastatic effect of obesity." (PMID 31817646, 2019). "Statistically, the concentrations of GROα, IL-2, IL-4, IL-6, IL-17A, IL-22, IL-23, and MCP-3 were significantly higher in males with obesity compared to the females with obesity, while the concentrations of IL-5, IL-10, IL-18, MCP-1, and MIP2α trended higher (p ≤ 0.1)." (PMID 41488663, 2025). "In children with overweight/obesity, the levels of pro-inflammatory cytokines, particularly IL-5, IL-17A, IL-33, TNF-α, and leptin, were also elevated, which is consistent with previous findings, indicating chronic low-grade inflammation associated with obesity." (PMID 39902293, 2024). "In the future, further study of approved anti-IL-5 biologic therapies may help clarify eosinophils’ role in obesity." (PMID 39200943, 2024). "Interestingly, obesity‐related leptin concentration significantly increased the ability of purified CD4+ T cells from lean AA patients to produce IL‐5, IL‐13, IL‐17 and IL‐6, but diminished IL‐10 release." (PMID 35734271, 2022). "The increased levels of IL-10 and IL-13 and decreased levels of IL-5 might be involved in maintaining immune tolerance during the initial stage of obesity, but later, might indirectly support M1 macrophage function to maintain chronic inflammation." (PMID 35456006, 2022). "Unanswered questions include how the levels of type 2 inflammation, such as cytokines IL4, IL13, IL5, and adiponectin levels, both systemically but also locally in the airways, are affected in our model from the different stages of obesity and allergic inflammation." (PMID 33256137, 2020). "Thus, IL-33 had a protective effect against obesity, insulin resistance and diabetes in animal models due to the reduction of resistin expression, accumulation of Th2 cells and IL-5, IL-13 and the suppression of T effectors cells by IL-10 releasing." (PMID 32824505, 2020). "Examination of mechanisms potentially responsible for diminished total colonic fecal IgA in obesity revealed a site-specific loss in factors promoting IgA production, such as TGF-β1 and IL-5, along with decreased expression of enzymes required for the synthesis of RA." (PMID 31409776, 2019). "In future research, it might be promising to consider the role of anti-inflammatory cytokines such as IL-5, IL-10 and IL-13 in relation to physical activity in staying metabolically healthy despite the presence of obesity." (PMID 25781614, 2015). "Of the cytokines studied, IL-5 concentrations showed the strongest correlation with adipometrics and may be a possible research and drug target in obesity." (PMID 25781614, 2015). "Visceral and subcutaneous LECs displayed an obesity-associated upregulation of the RAGE pathway, integrins and ECM–receptor interactions, while a downregulation in the brain-derived neurotrophic factor (BDNF), interleukin-5 (IL-5), IL-2 and AP1 networks was observed." (PMID 36400935, 2022). "First, obesity may worsen the prognosis of anti-IL-5-mAb therapy." (PMID 36498632, 2022).
Obesity (continued). "Furthermore, the authors demonstrated that eosinophil-knockout mice, generated from dblGATA mice, exhibited exacerbated obesity-induced IR, whereas a higher number of eosinophils, due to overexpression of IL-5 or helminth infections, improved obesity-induced IR." (PMID 29387059, 2017). "However, levels of IL-5, IL-6, and IL-13 went down in a dose-dependent manner and it could be interpreted that BoE supplementation could ameliorate the obesity related inflammatory features in the circulation system." (PMID 29292401, 2017). "The results displayed that differentially expressed genes in dataset GSE7305 were significantly enriched in IL1 and megakaryocytes in obesity, photodynamic therapy-induced NFKB survival signaling, the IL5 pathway, MAPK signaling pathway, and other pathways." (PMID 37817158, 2023). "Nonetheless, the adipose protein profile indicates sex- and RELMα-dependent effects of diet-induced obesity, which correlates with increased proinflammatory CCL2, and decreased anti-inflammatory and Th2 cytokines, IL-10, GM-CSF, and IL-5, respectively." (PMID 37162190, 2023). "The expression of IL-4, IL-13, and IL-5 decreased in HFD-fed mice and was restored by berberine, indicating that ILC2s inhibit obesity-related intestinal inflammation." (PMID 38283340, 2023). "Our observed decrease in cytokines IL-5 and G-GCF in HFD-fed mice supports the previous findings of the anti-obesity effects of these cytokines." (PMID 35456006, 2022). "In fact, IL-6 is one of the primary mediators of low-grade inflammation in obesity and both CXCL-1 as well as IL-5 have been found to be altered in prediabetes." (PMID 32210914, 2020). "In similar studies, exposure to high fat diet during lactation (only) induced an early-onset obesity in offspring (C57BL/N mice) at 3 weeks of age, with increased expression of mRNAs of IL-5, IL-13, IL-17A and TNFα in the lung." (PMID 30700289, 2019). "In order to investigate the role of a broad range of pro- and anti-inflammatory cytokines in obesity, serum levels of TNF-α, IFN-γ, IL-2, IL-4, IL-5, IL-10, IL-12, IL-13, and GM-CSF were compared between obese and non-obese participants." (PMID 25781614, 2015). "Compared with asthmatic patients without obesity, those subjects with obesity exhibit elevated sputum IL‐5 and submucosal eosinophils." (PMID 40329860, 2025). "Likewise, in females with obesity, vaccinated mice had significantly lower levels of eotaxin, GM-CSF, GRO-α, IL-1β, IL-2, IL-5, IL-6, IL-12p70, IL-17A, IL-18, IP-10, MCP-1, MCP-3, MIP-1α, MIP-1β, MIP-2α, and TNF-α compared to unvaccinated controls." (PMID 41488663, 2025). "Our data also showed significant increase in the levels of TNF-β, IL-5, PTX3 in T1DM, T2DM and obesity groups in comparison to infected control group, whilst the levels of FOXP3 and IL-10 were increased in the infected groups in comparison to their noninfected controls." (PMID 37296126, 2023). "However, when obesity was induced with a high‐fat diet, CTRP3 transgenic mice had lower circulating levels of IL‐5, TNF‐α, sVEGF2, and sVEGFR3, and a higher level of soluble gp130." (PMID 26997632, 2016). "Levels of IL-12 were elevated in obesity, IFN-γ, IL-4, IL-5, IL-12 and IL-13 elevated in MetS." (PMID 25781614, 2015). "IL‐5 may play a vital role in the ILC2‐MDSC axis and obesity in TNBC." (PMID 38501542, 2024). "Furthermore, our results also revealed several common upstream regulators associated with immune regulation and resistance to obesity (IL-4, IL-5, IL-33, CD15, HGF, ANGPT2, VEGFA, and neuropilin 1 [Nrp1]), supporting a critical role of intestinal homeostasis in systemic pathogenesis of obesity." (PMID 36880999, 2023). "The pulmonary recruitment of total cells and eosinophils remained elevated by treatment with anti-IL-5 mAb, strongly suggesting that this cytokine does not play a role in the aggravation of the allergic eosinophilic inflammation in diet-induced obesity conditions." (PMID 24204674, 2013).